IGF1R (insulin like growth factor 1 receptor)
Diseases named in the same sentence as IGF1R in open-access papers (continued):
Sharing a sentence is not in itself a finding about the gene and the disease.
colorectal cancer (156 papers, 2009 to 2025). A primary or metastatic malignant neoplasm that affects the colon or rectum. "For example, decreased levels of miR-139, which targets IGF-1R in colorectal cancer, are associated with disease progression and metastasis." (PMID 39273251, 2024). "Stimulation by IGF-1 causes proliferation in vitro while blocking IGF1-R inhibits growth of colorectal cancer cells." (PMID 39328205, 2024). "Concurrent circulating levels of the insulin-like growth factor-1 receptor are associated with colorectal cancer development." (PMID 38483686, 2024). "Studies have demonstrated that IGF-1R overexpression was associated with disease progression, poor prognosis, and treatment resistance in breast cancer, esophageal adenocarcinoma, colorectal cancer, and squamous cell carcinoma." (PMID 38540176, 2024). "In our further survival analysis of patients with TCGA colorectal cancer demonstrated that tumor expression of IGF-1R and RAGE was associated with shorter overall survival (Figure, P=0.018;Figure,P=0.013) while IGF-1 was not correlated with the prognosis." (PMID 36890832, 2023). "The SUMOylation of IGF1R allows nuclear translocation of the transcriptional cofactor IGF1R, which is associated with drug resistance in colorectal cancer." (PMID 37777749, 2023). "As a result, we find that sustained translation of IGF-1R mRNA, which encodes one of the most potent cell survival effectors, promotes the survival of 5-FU-treated colorectal cancer cells." (PMID 35013311, 2022). "Expression of MYB has been associated with sensitivity to IGF1R inhibition by CP-751,871 in lung, breast, and colorectal cancer cell lines." (PMID 27532210, 2016). "Although dysregulation of IGF1R and miRNAs is associated with tumorigenesis in human colorectal cancer, little is known about miRNAs that act on IGF1R." (PMID 25474488, 2014). "The higher expression levels of IGF-1R are associated with a higher malignant pathologic grade and late stage of colorectal carcinomas." (PMID 24182354, 2013). "PPP is a potent inhibitor of IGF-1R, another growth factor receptor that has also been implicated in tumour angiogenesis in colorectal cancer and multiple myeloma." (PMID 22363483, 2012). "IGF1R has been implicated in the chemoradioresistance of colorectal cancer." (PMID 37582734, 2023). "Loss- and gain-of-function experiments of miR-378a-3p in colorectal cancer cells suggest that miR-378a-3p may regulate the expression of the insulin-like growth factor 1 receptor (IGF1R) as a target gene." (PMID 26255816, 2015). "Obesity and its related metabolic abnormalities, including insulin resistance, alterations in the insulin-like growth factor-1 (IGF-1)/IGF-1 receptor (IGF-1R) axis, and the state of chronic inflammation, increase the risk of colorectal cancer (CRC) and hepatocellular carcinoma (HCC)." (PMID 22312273, 2012). "The samples with high miR-497 expression had lower IGF-1R protein levels, and the colorectal cancer samples expressed higher levels of IGF-1R compared to normal tissue." (PMID 41153350, 2025).
colorectal cancer (continued). "IGF1R expression is significantly increased in colorectal cancer tissues and acts as a potent receptor in response to IGF2 stimulation leading to adverse outcomes." (PMID 38887298, 2024). "Other recent data show that IGF1 and IGF1R expression correlated with AGEs in colorectal cancer patients who also had type 2 diabetes mellitus 111]." (PMID 38892104, 2024). "Paracrine signals from CAFs are also mediated by IGF2 as, in fact, exposure of colorectal cancer cells to CAF-derived IGF2 increases the activation of the IGF1R and downstream signaling, including the Hippo–YAP1 pathway." (PMID 38892104, 2024). "Further evidence of IGF-1R’s role in regulating metabolism via the Warburg effect has also been shown in colorectal cancer." (PMID 37373357, 2023). "Among colorectal cancer patients nuclear IGF-1R levels were reported to be higher in metastatic tumors relative to paired untreated primary tumors and correlated with a worse prognosis." (PMID 37858153, 2023). "Monensin was shown to target multiple cancer-related signaling pathways such as Elk1, AP1, as well as Myc/max, and suppressed IGF1R expression via increasing IGF1 in colorectal cancer cells." (PMID 36896461, 2023). "It is suggested that monensin can down-regulate the expression of IGF1R in human colorectal cancer cells, which has a synergistic anti-proliferation effect with overexpression of IGF1." (PMID 36896461, 2023). "More recently linsitinib (OSI-906), a novel small-molecule dual IGF1R/IR kinase inhibitor, demonstrated anti-proliferative effects in vitro and in vivo in both stem like and colorectal cancer models." (PMID 36920947, 2023). "In colorectal cancer, nuclear localization of IGF‐1R increased in metastatic tumors compared to primary tumors and was associated with chemotherapy and IGF‐1R targeted therapy resistance." (PMID 37306107, 2023). "In IGF1R dependent colorectal cancer, linsitinib inhibited tumour growth in cell-line derived xenografts when treated with 40 mg/kg." (PMID 36920947, 2023). "Our study is in consistent with others observation that IGF1R inhibitor potentiates the efficacy of Anti-VEGF therapy against IGF2-Overexpressing colorectal cancer tumors." (PMID 35974000, 2022). "We find that upon 5-FU treatment, translation of the mRNA of the pro-survival IGF-1R gene is sustained, and promotes the survival of 5-FU-treated colorectal cancer cells." (PMID 35013311, 2022). "The IGF1 receptor (IGF1R) signaling cascade is activated in around 20% of colorectal cancer patients and leads to downstream mitotic stimuli via mitogen activated kinase signaling and mTOR58." (PMID 35668108, 2022). "A previous study demonstrated that IGF-1R is overexpressed in human colorectal cancer HT-29 cell lines." (PMID 35931997, 2022). "IGF-1/IGF-1R and miR-let-7e have been previously reported to downregulate each other and modulate proliferation and migration in colorectal cancer cells." (PMID 36062186, 2022). "Paracrine IGF1/IGF1R signaling initiated by radiotherapy-activated cancer-associated fibroblasts promotes colorectal cancer progression, and the radiation-induced secretion of IGF1 in human fibroblasts up-regulated IGF1R/Akt signaling in bystander cells." (PMID 34178997, 2021). "IGF2 can bind also to the IGF1R and to the insulin receptor isoform A (IR-A) exerting its mitogen effects which have been extensively studied especially in the context of colorectal cancer (CRC) as described in a recent review." (PMID 34484116, 2021). "In colorectal cancer, the expression of miR-424 and miR-497 co-target IGF1-R and are both down-regulated, but only the up-regulated expression of miR-497 will result in the inhibition of IGF1-R 3’UTR activity." (PMID 33841401, 2021). "Ectopic overexpression of ATP-citrate lyase and insulin-like growth factor 1 receptor rescues the decreased colorectal cancer metastasis induced by HOXA13 knockdown." (PMID 34722321, 2021).
colorectal cancer (continued). "Tang concluded that CDR1as can partially block miR-7 and positively regulate EGFR and insulin-like growth factor-1 receptor (IGF-1R) to promote colorectal cancer (CRC) progression." (PMID 32765960, 2020). "For example, in colorectal cancer, tumor growth and niche inflammation are both attenuated by the dual inhibition of IGF-1R signaling and the STAT3 pathway, resulting in much smaller tumor sizes in both primary and metastatic tumors." (PMID 33511137, 2020). "For example, CircHIPK3 promotes colorectal cancer growth and metastasis by sponging miR-7 to regulate insulin-like growth factor 1 receptor (IGF1R) expression." (PMID 32211228, 2020). "The insulin-like growth factor 1 receptor (IGF1R) is suspected to be involved in colorectal carcinogenesis and has been associated with worse survival in colorectal cancer (CRC)." (PMID 32727431, 2020). "The Insulin-like growth factor-I/Insulin-like growth factor-I receptor (IGF-1/IGF-1R) system is a major determinant in colorectal cancer (CRC) pathogenesis." (PMID 31480481, 2019). "Inhibiting IGF-1 and IGF-1R signalling has shown promising results in colorectal cancer by blocking the influence of its microenvironment." (PMID 31076571, 2019). "In summary, the results from the current study show that curcumin inhibits the cell proliferation and migration of chemoresistant colorectal cancer cells, along with a marked attenuation of IR, IGF-1R, and MYC expression." (PMID 30987250, 2019). "The region of gain of chromosome 1p included the colorectal cancer-associated genes REG4 and NOTCH2 and gain of 15q included the genes MAP2K1, SMAD3, SMAD6, and IGF1R, among others." (PMID 31620944, 2019). "Overexpression of miR-448 suppresses proliferation and invasion by regulating IGF1R in colorectal cancer cells." (PMID 29483929, 2018). "One study reported similar blocking of IGF‐1R signalling activation that induced cytostatic effects in colorectal cancer cells." (PMID 30247804, 2018). "Our previous study also demonstrated that KL functioned as a tumor suppressor in colorectal cancer by inhibiting the IGF1R-mediated PI3K/AKT pathway." (PMID 29884183, 2018). "AKAP1 was shown to be required for cAMP-dependent PKA mediated apoptosis in colorectal cancer cells upon IGF1R inhibition." (PMID 29433456, 2018). "Four datas from three studies described the OS-colorectal cancer (HR = 1.29, 95% CI = 1.05-1.59), revealing significantly worse effects on colorectal cancer patients that treated with IGF-1R inhibitors." (PMID 28427155, 2017). "IGF1R is a transmembrane tyrosine protein receptor with tyrosine kinase activity and frequently overexpresses in various cancers including colorectal cancer." (PMID 29156819, 2017). "MiR-139 reportedly target Rho-kinase 2 in hepatocellular carcinoma 11, NR5A2 in esophageal cancer 14, NOTCH1 and IGF1R in colorectal cancer 15,28." (PMID 26256448, 2015). "Recent studies have demonstrated that IGF-1R plays a crucial role in the oncogenesis and development of colorectal cancer." (PMID 26307972, 2015). "Numerous evidences have confirmed that IGF-1R was a promising target for cancer therapy, which was overexpressed in colorectal cancer (CRC), and mediated anti-apoptosis activity in CRC development." (PMID 26307972, 2015). "It has been reported that IGF-1R was overexpressed in more than 90% colorectal carcinomas, which contributed to the malignant characteristics of aggressive growth and poor prognosis." (PMID 26307972, 2015). "In this study, miR-143 and miR-145 showed an anti-tumor effect invitro through the negative regulation of IGF1R in human colorectal cancer." (PMID 25474488, 2014). "In this study, we found that IGF1R was directly regulated by miR-143 and miR-145 in colorectal cancer cells." (PMID 25474488, 2014). "In conclusion, our results demonstrated that miR-143/145 directly recognizes and binds to the 3′-UTR of the IGF1R mRNA transcript to suppress IGF1R expression in colorectal cancer cells." (PMID 25474488, 2014).
colorectal cancer (continued). "Taken together, our findings provide evidence for a role of the miR-143/145 cluster as a tumor suppressor in colorectal cancer through the inhibition of IGF1R translation." (PMID 25474488, 2014). "We characterized the mechanisms by which a novel Akt kinase inhibitor MK-2206 induced cell death in IGF1R-dependent colorectal cancer (CRC) cells with upregulated PI3K/Akt signaling in response to IGF1R activation." (PMID 24581231, 2014). "We found IGF-1R was a direct target of miR-497 by a luciferase reporter assay, which was also reported in colorectal cancers and cervical cancers." (PMID 24667580, 2014). "The correlation between miR-143/145 and IGF1R was further examined by evaluating IGF1R expression in the human colorectal cancer cell lines Caco2, HT29 and SW480 after overexpression of miR-143/145." (PMID 25474488, 2014). "Because IGF1R is essential for the regulation of proliferation and cell cycle progression, we evaluated the effects of miR-143/145 on colorectal cancer cell proliferation using a CCK-8 assay." (PMID 25474488, 2014). "Recently, an important role for IGF1R in the genesis and progression of colorectal cancer has emerged." (PMID 25474488, 2014). "Downregulation of miR-497 contributes to the malignancy of colorectal cancer and cervical cancer by upregulating IGF-1R." (PMID 24667580, 2014). "In this study, few patients with chemotherapy-refractory colorectal cancer appeared to benefit from treatment with the IGF-1R antagonist robatumumab." (PMID 24905030, 2014). "Consistent with the bioinformatic analyses, we identified an inverse correlation between miR-143/145 levels and IGF1R protein levels in colorectal cancer tissues." (PMID 25474488, 2014). "Interest in the miR-143/145 cluster and IGF1R was also supported by the recent identification of these two miRNAs as candidate tumor suppressors and IGF1R as an oncogene in colorectal cancer." (PMID 25474488, 2014). "While high expression levels of the IGF-1R have been found in breast and colorectal cancer, autocrine signaling loops are more common, and have been reported in a wide variety of human malignancies." (PMID 23525758, 2013). "The dependence of malignant properties of colorectal cancer (CRC) cells on IGF1R signaling has been demonstrated and several IGF1R antagonists are currently in clinical trials." (PMID 24083380, 2013). "IGF1R is often overexpressed and upregulated in many cancer types, including colorectal cancer (CRC)." (PMID 24083380, 2013). "Past studies have shown that amplified insulin-like growth factor 1 (IGF1)/IGF1 receptor (IGF1-R) signalling has an important role in colorectal cancer (CRC) development, progression and resistance to treatment." (PMID 22710713, 2013). "Signaling through IGF-1R mediates cell growth and proliferation as well as resistance to apoptosis in all major solid tumors, including colorectal cancer." (PMID 23921573, 2013). "Preclinical studies have shown that the GEO colorectal carcinoma cell line and xenografts respond to the treatment of a dual IGF-1R/insulin receptor kinase inhibitor, PQIP." (PMID 24182354, 2013). "There is growing evidence indicating the insulin-like growth factor 1 receptor (IGF-1R) plays a critical role in the progression of human colorectal carcinomas." (PMID 24182354, 2013). "We then examined a panel of seven colorectal carcinoma cell lines by western blotting and identified the expression of IGF-1R in each of these cell lines." (PMID 24182354, 2013). "By activating PI3K/AKT and ERK growth pathways and inhibiting the BAD and TNFα-mediated apoptosis, the IGF-1R signaling pathway promotes the survival, growth, and metastasis of colorectal carcinomas." (PMID 24182354, 2013).
colorectal cancer (continued). "To examine the expression of IGF-1R protein, we carried out a western blot analysis of human colorectal carcinoma tumors, together with matched normal colorectal tissue." (PMID 24182354, 2013). "In this study, we investigated the therapeutic response of human colorectal carcinomas with the recently identified IGF-1R inhibitor, PPP." (PMID 24182354, 2013). "In this study, semi-quantitative RT-PCR analyses of 48 paired, colorectal cancer patient samples showed significant overexpression of tumor IGF-1R and IGF-2 mRNA." (PMID 22159423, 2012). "For example, in a survey of 41 breast and 27 colorectal cancer cell lines, the expression levels of IGF-1R, IRS-1, IRS-2, and IGF-2 were correlated with positive predictive values for h10H5." (PMID 22952934, 2012). "Several anti-IGF1R agents in combination with cytotoxic and other targeted agents are currently in clinical development for more common cancers such as lung and colorectal cancer." (PMID 21052545, 2011). "In colorectal cancer, IGF1R inhibits the let‐7 microRNA family, promoting malignant progression." (PMID 38292328, 2024). "In addition, IGF-1R has been well-studied for use in prognostic predictions in various malignancies, such as breast, prostate, lung, and colorectal cancers." (PMID 38540176, 2024). "IGF1R heterozygous knockout mice are also protected from colitis and colorectal cancer due to the enhanced preservation of mitochondrial structures and dynamics, alongside increased mitochondrial electron transport chain activation in conditions of oxidative stress." (PMID 38706850, 2024). "Moreover, the synergistic anti-tumor activity of an anti-PD-1 antibody in combination with PB-020, a novel PPP-derived small-molecule inhibitor of IGF1R with improved pharmacokinetic properties, has been demonstrated in a mouse model of colorectal cancer." (PMID 38420122, 2024). "It suggests that monensin combined with treatment targeting IGF1R or IGF1 may potentiate anti-cancer effect in colorectal cancer, which needs further investigation." (PMID 36896461, 2023). "A study has demonstrated that the expression level of IGF1R within the nuclear compartment might lead to metastasis and therapies resistance in colorectal cancer." (PMID 36843983, 2023). "We seek to investigate the effect of monensin on proliferation of human colorectal cancer cells and explore whether IGF1R signaling pathway is involved in anti-cancer mechanism of monensin." (PMID 36896461, 2023). "IGF1R activation drives the development and malignant progression of colorectal cancer." (PMID 35651701, 2022). "It had been revealed that circ_0067835 knockdown could suppress cell progression and enhance cell radiosensitivity of colorectal cancer partially by sponging with miR-296-5p/IGF1R axis." (PMID 36262967, 2022). "We already demonstrated for colorectal cancer that this role had been wrongfully assigned and that this might explain why trials with IGF1R inhibitors had failed in this cancer entity." (PMID 34638472, 2021). "Besides, miRNA-532 was shown to inhibit the development of colorectal cancer by directly targeting IGF1R to inhibit the PI3K/Akt pathway." (PMID 34761108, 2021). "Furthermore, the amount of nuclear IGF-1R serves as an effective predictor of anti-IGF-1R therapy in sarcoma and of drug resistance in liver cancer cells and colorectal cancers." (PMID 33511137, 2020). "A study reported that miR-625-5p targeted IGF1R in colorectal cancer cell line." (PMID 32847606, 2020). "Also, miR-378a-5p was recognized as a tumor suppressor to reduce cell proliferation and colony formation in colorectal cancer by targeting IGF1R through activating of AKT/ERK pathway." (PMID 32348429, 2020). "MicroRNA-497 has been reported to inhibit thyroid cancer tumor growth and invasion by suppressing BDNF, which is involved in cell proliferation and invasion of gastric cancer by repressing eIF4E, and to inhibit colorectal cancer growth by targeting insulin-like growth factor 1 receptor." (PMID 33015042, 2020).